INS (insulin)
Diseases named in the same sentence as INS in open-access papers (continued):
Sharing a sentence is not in itself a finding about the gene and the disease.
Hypoglycemia (continued). "The glucose, glucose kinetics, and glucagon data were previously published as part of a report focusing on glucose counterregulatory response to insulin-induced hypoglycemia among GB and SG subjects." (PMID 35887007, 2022). "Glucagon, the counterregulatory hormone to insulin, increases in response to hypoglycemia and extended fasting to promote hepatic glycogenolysis and increase blood glucose." (PMID 36315375, 2022). "When examining the corpses of people with reasonable suspicion of death due to hypoglycemia due to insulin overdose, it is important to look for the injection place." (PMID 35324747, 2022). "A serious adverse effect of insulin therapy is hypoglycemia that results in emergency room visit or hospitalization." (PMID 35189851, 2022). "ISF brain glucose levels are stable during the initial stage of insulin-induced hypoglycemia, indicating that the afferent signals of changes in the circulating blood glucose should not be derived from those glucose-sensing neurons, including those in the VMH." (PMID 35619170, 2022). "A subsequent in vivo study proved that iontophoresis induces hypoglycemia in rats treated with insulin-loaded mucoadhesive patches." (PMID 35890301, 2022). "Before using an open-source AID, many caregivers were not able to sleep through the night as they were concerned with nighttime hypoglycemia or the administration of correction doses of insulin, poor sleep, and reduced quality of life." (PMID 35834298, 2022). "Of note, changes in the application of PN afford an instant adaptation of the insulin regimen in order to prevent hypoglycemia." (PMID 36992742, 2022). "Nocturnal hypoglycemia was prevented by intravenous infusion of glucose on one day and induced by intravenous insulin on another day." (PMID 36237834, 2022). "Further studies are required to assess functional interactions between islet cell populations following RYGB and possible involvement of loss of somatostatin-induced inhibitory tone from delta-cells in insulin-induced hypoglycemia." (PMID 36137097, 2022). "A CAGE/CPVA insulin patch was further tested on an in vivo model, and sustained hypoglycemia was observed in rats with varying doses of insulin." (PMID 35890301, 2022). "Short-acting insulin analogs were disclosed for their opposite effects involving hypoglycemia, impaired gait, tiredness, roseola, and bilateral leg edema." (PMID 35723344, 2022). "Routine prophylactic administration of insulin is dangerous, leading to hypoglycemia and even death." (PMID 35237639, 2022). "Interventions delivered by research teams, besides imparting basic education and self-management skills, also touched upon more technical points on the kinetics of insulin and cues signaling hypoglycemia and management of medicine." (PMID 36145181, 2022). "In contrast, during nutritional rehabilitation, increased glucose load provokes postprandial insulin surges which can provoke post-prandial hypoglycemia in a pathophysiology similar to the dumping syndrome." (PMID 35011105, 2022). "Though insulin therapy attempts to maintain normal glucose homeostasis in T1D patients, iatrogenic hypoglycemia due to impaired insulin–glucagon counter-regulatory responses is a major shortcoming of this treatment." (PMID 36686451, 2022). "Decreased insulin secretion and less hypoglycemia are likely consequences of the reduction in viable tumors." (PMID 35118189, 2022). "The real strength of the artificial pancreas system is in regulating basal insulin injections to change the glycemic status (both hyperglycemia and hypoglycemia)." (PMID 36494830, 2022). "Among people who use premixed insulin and have an HbA1c < 7%, more attention needs to be paid on hypoglycaemic events and asymptomatic hypoglycaemia." (PMID 35574003, 2022). "When insulin pumps were first used, a history of severe hypoglycemia was a key determining factor for commencement of pump therapy." (PMID 35757419, 2022).
Hypoglycemia (continued). "Anticipating insulin-induced postprandial hypoglycemic events is exigent because the primary cautioning of hypoglycemia simplifies the rectification of the insulin bolus before its execution." (PMID 36572938, 2022). "Patients who were treated with premixed-based insulin regimen were found more likely to have hypoglycemia (34.6%) compared with those treated by NPH-based insulin regimen (2.9%) (p < 0.001)." (PMID 36149907, 2022). "Particularly relevant to our research is the observation that antioxidant treatments can normalize fasting‐induced hypoglycemia and increase insulin sensitivity." (PMID 35932179, 2022). "In clinical practice, very few events (such as hypoglycemia during an insulin treatment) can be related to drug prescriptions with a causality rating of ‘certain’." (PMID 36615115, 2022). "For example, an insulin-hypoglycemia test with a glucose level below 2 mmol/L resulted in an almost threefold increase in copeptin levels in healthy adults." (PMID 35723775, 2022). "Insulin injection in mice induced accelerated jejunal transport independently of hypoglycemia, by activating cholinergic and adrenergic systems." (PMID 36117310, 2022). "Ch-PSS-PGA NPs resulted in 1.7-fold higher cumulative hypoglycemia when compared to subcutaneously administered insulin." (PMID 35890301, 2022). "Since then, the patient became hyperglycemic but the insulin doses were progressively reduced until new episodes of hypoglycemia recurred and the insulin was stopped." (PMID 36225520, 2022). "It is useful for users to review what insulin has been delivered by closed-loop to determine appropriate hypoglycemia treatment." (PMID 32914648, 2022). "were the first to report a comprehensive description of metabolomic changes within 24 hours of insulin-induced hypoglycemia in T2DM patients." (PMID 35784552, 2022). "Nocturnal hypoglycemia (NH) is a wide-spread and potentially dangerous complication of insulin therapy which often goes undetected." (PMID 36013211, 2022). "The diagnosis of HH due to nesidioblastosis is based on the clinical presentation of hypoglycemia, and biochemical profile that arises from the anabolic effects of increased serum insulin concentration." (PMID 35296370, 2022). "Comparison of the prevalence of hypoglycaemia by insulin (dose, rate of infusion, type, and timing relative to dextrose) and dextrose (dose and rate of infusion)." (PMID 35552566, 2022). "Multiple precautions must be taken to prevent hypoglycaemia, i.e. physical activity should be started close to hyperglycaemia (approximately 1.8 g/l) and the basal insulin flow must be reduced before and during activity." (PMID 35577814, 2022). "Empagliflozin also exacerbates hypoglycemia in patients taking potent glycemic-lowering treatments such as insulin and insulin-secreting drugs." (PMID 36552050, 2022). "Pancreatic β-cells promote nutrient uptake in the post-prandial state via the release of insulin, whereas, in a fasted state, β-cells suppress insulin secretion to prevent hypoglycemia." (PMID 35204835, 2022). "This included practical support to check blood glucose or inject insulin, manage diet and treat hypoglycaemia, and it also included encouragement and emotional support to facilitate autonomy and learn skills." (PMID 35983585, 2022). "While some positive effects on HbA1c, in particular in people with preserved insulin secretion, were observed, with a neutral effect on hypoglycemia, research in this field has petered out in the last decades and SUs do not play a role in people with T1D." (PMID 35745754, 2022). "Due to sever acidosis association with fetal death, it is one of the mainstays of treatment, early detection and timely administration of fluids, carbohydrates, and insulin, to prevent hypoglycemia." (PMID 36483858, 2022). "CD4+ and CD8+ T cell counts significantly decreased, insulin use reduced, and hypoglycemia was attenuated." (PMID 36389806, 2022).
Hypoglycemia (continued). "During hypoglycaemia, their median insulin level was 20.3 mUI/L (IQR: 19–20.3) and their C‐peptide level was 2.79 μg/L (IQR:0.79–2.79)." (PMID 36117266, 2022). "Throughout the literature, hypoglycemia is identified as one of the essential patient-related factors contributing to insulin avoidance and fear of insulin." (PMID 35457303, 2022). "Accordingly, we used an already established rat model of decreased maternal glucose supply, consisting of continuous insulin-induced hypoglycaemia, shown to be accompanied by decreased/delayed foetal growth." (PMID 35344549, 2022). "This study aimed to develop a predictive scoring model that can predict the occurrence of hypoglycemia after administering 10 units of IV regular insulin with 25 g of glucose for the treatment of hyperkalemia." (PMID 36371171, 2022). "Male and female Agpat5flox/flox and Sim1Agpat5KO mice displayed identical body weight, glucose tolerance, insulin sensitivity, and hypoglycemia-stimulated glucagon secretion." (PMID 36180454, 2022). "Among the short-term consequences, the most common is fetal hypertrophy, which results in macrosomia at birth, but also insulin resistance that develops in the prenatal period, and postnatal hypoglycemia, which can be life-threatening for the child." (PMID 36077491, 2022). "It would be necessary to extend the diagnosis of CAI by performing an overnight metyrapone test or the insulin-induced hypoglycemia test." (PMID 36465638, 2022). "Our data are in concordance with a study in which hypoglycemia was reported after insulin injection in VPAC1 null mice." (PMID 35336804, 2022). "The new insulin analogues appear as a potentially favourable therapy in the AM frail phenotype as long as hypoglycaemia is avoided." (PMID 35723859, 2022). "There was a 32% reduction in episodes of severe hypoglycemia [RR 0.68 (95% CI 0.60–0.77)] and a 45% reduction in nocturnal hypoglycemia episodes [RR 0.55 (95% CI 0.40–0.76)] in favor of the rapid-acting insulin analogues." (PMID 36510287, 2022). "Patients who were treated with a premixed insulin-based regimen were found 96.7% more likely to have hypoglycemia than patients initiated with NPH insulin [AOR = 0.033, 95% CI (0.009–0.119); p < 0.001]." (PMID 36149907, 2022). "The population at risk of drug-induced hypoglycemia is significant, with nearly 20% to 30% of patients with T2DM requiring insulin." (PMID 35343912, 2022). "In particular, it is considered to have a significant effect on hypoglycemia because it can learn the details of a patient's daily life (e.g., timing, and the duration and intensity of meals and exercise) to optimize insulin infusions." (PMID 36494830, 2022). "Of the 31 cats receiving insulin and dextrose that were evaluated for the development of hypoglycemia, nine (29%) received dextrose supplementation only as a bolus with the first dose of insulin." (PMID 36350735, 2022). "As expected, the mean basal insulin dose requirements were significantly higher for the basal–bolus group, and a lower number of grade 1 hypoglycemia was observed in the basal–DPP4-i group." (PMID 35628938, 2022). "Despite therapies (e.g. insulin analogs) and new technologies (e.g. continuous glucose monitoring (CGM)), the risk of hypoglycemia remains high, especially at night." (PMID 36237197, 2022). "Sensor augmented pumps (for example, MiniMed 640G and the newer MiniMed 780G systems) have special software which allows the user to customize when the pump should suspend insulin delivery in the context of hypoglycemia." (PMID 36422210, 2022). "The CONCLUDE trial, involving people with T2D switching from 1BIs to Gla-300 or the new 200 U/mL formulation of insulin degludec, documented a similar rate of overall symptomatic hypoglycemia during the 36-week maintenance period." (PMID 35864262, 2022). "In most insulin trials investigating effects on memory or AD, insulin is delivered by intranasal administration to avoid hypoglycemia." (PMID 35128745, 2022).
Hypoglycemia (continued). "The fact that both insulin and glucagon concentrations were reduced suggests that the fetal hypoglycemia induced by SLC2A3 RNAi during the first half of gestation had an overall effect on pancreas development and growth, rather than a β cell-specific effect." (PMID 36293384, 2022). "On the other hand, continuous glucose monitoring systems (CGMS) allow for the control of asymptomatic hypoglycemia, especially during sleep, thanks to which it is possible to adjust the insulin dose and prevent further hypoglycemic episodes." (PMID 35620854, 2022). "In other words, the ISF glucose level does not represent the temporal dynamics of the glucose in circulation during insulin-induced hypoglycemia." (PMID 35619170, 2022). "Nevertheless, if there is physical activity, but the algorithm does not recognize it, it can happen that the regular dosage of the administered insulin leads to hypoglycemia, which is a dangerous condition that can be tolerated only in the short term." (PMID 36366265, 2022). "In this context, a prolonged 24 hour fast precipitated early hypoglycemia with plasma glucose of 2.7 mmol/L and a concurrent suppressed serum insulin, c-peptide, proinsulin and 3-hydroxybutyrate." (PMID 36303203, 2022). "Hypoglycemia was described only when empagliflozin was combined with insulin or insulin secretagogues (e.g., sulfonylurea) in diabetic patients." (PMID 35822097, 2022). "Its mechanism of action is insulin-independent, which increases glucose excretion in urine and thus protects the patient from side effects like hypoglycemia that occur in patients on oral hypoglycemic agents." (PMID 36523727, 2022). "In summary, tirzepatide achieved more pronounced HbA1c reductions with a lower incidence of hypoglycemia at week 52 compared to insulin glargine." (PMID 36313764, 2022). "Autoantibodies directed against insulin and its receptor Syndromes of autoimmunity and hypoglycemia." (PMID 34698875, 2022). "A significant concern for the ITT is the need for administering a second insulin dose to achieve adequate hypoglycaemia, thus prolonging the testing." (PMID 35465075, 2022). "Adrenocorticotropin hormone and cortisol responded poorly to both insulin-induced hypoglycemia and CRH administration." (PMID 35281581, 2022). "The authors proposed that the increased GLP-1 levels potentiated the insulin surge and contributed to the subsequent hypoglycemia." (PMID 35399928, 2022). "Reasonable diet control can not only reduce insulin load and correct metabolic disorders but also prevent the failure of blood glucose control and hypoglycemia." (PMID 36091592, 2022). "Owing to the complications of therapy, hypoglycemia, and the probability of weight increase, attaining and keeping the goal level of HbA1c by insulin optimization strategies remains a primary problem for T1DM." (PMID 35872994, 2022). "In the tight glucose control group, glucose control is guided by the validated LOGIC-Insulin algorithm, which was shown to lead to effective and high-quality glucose control, with a very low incidence of hypoglycemia." (PMID 36123593, 2022). "Hypoglycemia results from a mismatch between insulin and carbohydrate intake, exercise, or alcohol consumption." (PMID 36149907, 2022). "Surprisingly, hypoglycemia was registered in only 1596 patients (1.2%), out of which 73.2% were on insulin, 9% on sulfonylureas, and 8.7% on glinides." (PMID 36079064, 2022). "Included in this passive experience was a sense of trust that technology would suspend delivery of insulin if the user was moving towards hypoglycaemia." (PMID 35627851, 2022). "As a result, patients receiving chronic insulin therapy undergo episodes of poorly compensated hypoglycaemia and in many cases develop impaired perception of hypoglycemia." (PMID 35207609, 2022). "A 72 hour fast with results showed early hypoglycemia and suppression of serum insulin, c-peptide, and proinsulin." (PMID 36303203, 2022).
Hypoglycemia (continued). "A comprehensive examination observed lesser variability among lispro, aspart, and human regular insulin for hemoglobin A1c and a lesser possibility of acute hypoglycemia with insulin preparations." (PMID 35723344, 2022). "The only case of CHARGE syndrome with reported insulin levels showed hyperinsulinemia in infancy with severe hypoglycemia soon after birth." (PMID 36232804, 2022). "RIP-Tag mice rapidly develop highly penetrant functional PanNETs (which are predominantly insulinomas), and mice succumb to hypoglycemia induced by the high levels of insulin produced by the tumors." (PMID 35976056, 2022). "It remains possible that alpha cell dysfunction is presently lost prior to decreasing insulin secretion leading to hypoglycemia in future progressors." (PMID 36171903, 2022). "The concern of hypoglycemia is a barrier to successful hyperglycemic control, as it encourages insulin underdoing." (PMID 35862181, 2022). "For patients who use premixed insulin and with HbA1c < 7%, more attention needs to be given to hypoglycaemic events and asymptomatic hypoglycaemia." (PMID 35574003, 2022). "Congenital hyperinsulinism (CHI) is a rare genetic condition characterized by uncontrolled insulin secretion, resulting in hypoglycemia." (PMID 36202918, 2022). "Previous studies in adult male di/di rats suggested that both immune challenge by intravenous (IV) egg white and hypoglycaemia-inducing insulin injections (as a metabolic stressor) resulted in reduced ACTH levels compared to respective controls." (PMID 35163282, 2022). "In comparison, those who had an HbA1c ≥53 mmol/mol on SU spent 0.0% (IQR: 0.00–0.92) and those on insulin spent 1.27% (0.00–5.75) of their total time per week in hypoglycemia (<3 mmol/L)." (PMID 35450869, 2022). "There is a large body of preclinical evidence implicating GABAergic neurotransmission in the VMN in the etiopathology of recurrent iatrogenic hypoglycemia induced by insulin therapy." (PMID 35207609, 2022). "Hypoglycemia can be the consequence of improved insulin action due to metreleptin treatment, usually seen in diabetic patients in simultaneous therapy with insulin or oral hypoglycemic drugs." (PMID 35600578, 2022). "Central obesity has been associated with metabolic syndrome that includes dyslipidemia, decreased insulin sensitivity, hyperinsulinemia, hypoglycemia, and hypertension." (PMID 35145215, 2022). "According to a clinical investigation, fenugreek improves insulin sensitivity and thus hypoglycemia management." (PMID 35268815, 2022). "Hypoglycemia was over 16 times more common in those who received insulin for glycemic control (OR = 16.5; 95% CI: 1–312; p = 0.01)." (PMID 35457586, 2022). "Insulin is also a vital regulator of brain glucose metabolism, and hypoglycaemia can induce migraine attacks in CM patients following prolonged fasting." (PMID 35627115, 2022). "Repeated hypoglycaemia induced by insulin attenuates the endocrine counter-regulatory response to hypoglycemia, which normally involves a marked increase of plasma glucagon, norepinephrine and cortisol." (PMID 35207609, 2022). "2.Basal insulin was stopped during the following 2–4 h to account for the increased levels of active insulin in circulation after intake of the bolus to prevent hypoglycemia." (PMID 35351180, 2022). "Our case also stresses again the need to test IAs in patients presenting with intractable hypoglycaemia under insulin therapy." (PMID 36440205, 2022). "Variable glucose responses to the same activity, uncertainty in how best to manage insulin therapy, and the fear of hypoglycaemia prevail as major barriers to regular exercise participation." (PMID 36147573, 2022). "In particular, hypoglycemia is known as a symptom that occurs frequently in patients with T1D due to inadequate dosage and timing of sulfonylureas or insulin used for treatment." (PMID 36494830, 2022).